ENSG00000255339 (NADH dehydrogenase (ubiquinone) 1 beta subcomplex, 8, 19kDa (NDUFB8) and SEC31 homolog B (S. cerevisiae) (SEC31B) readthrough)
Gene: Protein-coding gene on chromosome 10 (100,505,628 to 100,529,881, reverse strand). Ensembl gene ENSG00000255339.
Genetic constraint (gnomAD): Missense variants: 223 observed, 238.71 expected, observed/expected ratio (o/e) 0.93, 90% interval 0.84 to 1.04. Synonymous variants: 82 observed, 87.27 expected, observed/expected ratio (o/e) 0.94, 90% interval 0.79 to 1.13.